SLC17A9 (solute carrier family 17 member 9)
Description:
Voltage-gated ATP nucleotide uniporter that can also transport the purine nucleotides ADP and GTP. Uses the membrane potential as the driving force to control ATP accumulation in lysosomes and secretory vesicles. By controlling ATP storage in lysosomes, regulates ATP-dependent proteins of these organelles. Also indirectly regulates the exocytosis of ATP through its import into lysosomes in astrocytes and secretory vesicles such as adrenal chromaffin granules, mucin granules and synaptic vesicles.
Synonyms: VNUT; C20orf59; FLJ23412; POROK8
Tractability: Antibody: UniProt predicts a signal peptide or a membrane-spanning region.
Gene: Protein-coding gene on chromosome 20 (62,952,668 to 62,969,585, forward strand). Ensembl gene ENSG00000101194.
Subcellular location: Cytoplasmic vesicle, secretory vesicle, chromaffin granule membrane; Cytoplasmic vesicle, secretory vesicle membrane; Lysosome membrane
Subcellular location (Human Protein Atlas): Nucleoplasm
Gene Ontology:
Molecular function: ADP transmembrane transporter activity; ATP transmembrane transporter activity; guanine nucleotide transmembrane transporter activity; protein binding; purine nucleotide uniporter activity; transmembrane transporter activity
Biological process: ADP transport; ATP export; ATP transport; guanine nucleotide transmembrane transport; purine nucleotide import into lysosome; purine-containing compound transmembrane transport; transmembrane transport
Cellular component: mucin granule; chromaffin granule membrane; lysosomal membrane; membrane; secretory granule; transport vesicle membrane
Genetic constraint (gnomAD): Loss-of-function variants: 51 observed, 56.2 expected, observed/expected ratio (o/e) 0.91, 90% interval 0.72 to 1.15. The upper end of that interval is the gene's LOEUF score, 1.15, which puts it in group 5 of 6, group 1 being the genes least tolerant of losing a copy. Missense variants: 524 observed, 566.63 expected, observed/expected ratio (o/e) 0.92, 90% interval 0.86 to 0.99. Synonymous variants: 256 observed, 247.41 expected, observed/expected ratio (o/e) 1.03, 90% interval 0.93 to 1.15.
Homologues: Orthologues: chimpanzee SLC17A9 (99% identical), macaque SLC17A9 (96% identical), dog SLC17A9 (89% identical), pig SLC17A9 (88% identical), guinea pig SLC17A9 (83% identical), mouse Slc17a9 (82% identical), rat Slc17a9 (82% identical), rabbit SLC17A9 (73% identical), tropical clawed frog SLC17A9 (60% identical), zebrafish slc17a9b (57% identical), zebrafish slc17a9a (47% identical), Drosophila melanogaster MFS18 (38% identical), and 1 more. Paralogues in human: SLC17A5 (27% identical), SLC17A7 (26% identical), SLC17A6 (25% identical), SLC17A8 (25% identical), SLC17A2 (25% identical), SLC17A4 (24% identical), SLC17A3 (23% identical), SLC17A1 (22% identical), SLC37A1 (17% identical), SLC37A2 (17% identical), SLC37A4 (17% identical), SLC37A3 (14% identical).
Diseases named in the same sentence as SLC17A9 in open-access papers:
SLC17A9 is named in the same sentence as 44 diseases in open-access papers, as found by Europe PMC text mining. Sharing a sentence is not in itself a finding about the gene and the disease. The quoted sentences say what the papers report.
colorectal cancer (4 papers, 2021 to 2023). A primary or metastatic malignant neoplasm that affects the colon or rectum. "SLC17A9 is thought to be a disease‐related gene associated with disseminated superficial actinic porokeratosis, a rare autosomal dominant genodermatosis, gastric carcinoma and colorectal cancer." (PMID 35505881, 2022). "Solute carrier family 17 member 9 (SLC17A9) was involved in the progression of colorectal cancer (CRC) and breast cancer and was recognized as a potential biomarker for outcome prediction of CRC and BC patients." (PMID 37964984, 2023). "High SLC17A9 expression correlates with poor survival in hepatocellular carcinoma, gastric carcinoma, and colorectal cancer." (PMID 34993155, 2021). "It has been reported that SLC17A9 upregulation is related to the dismal prognostic outcome of GC and colorectal cancer (CRC)." (PMID 34900992, 2021).
diabetes (3 papers, 2017 to 2019). "In this commentary, we advance the hypothesis that SLC17A9 dysfunction may contribute to the ongoing inefficacy of insulin exocytosis, leading to progressive diabetes." (PMID 28210227, 2017). "SLC17A9 may be tagged and imaged with similar novel methodologies to estimate whether their quantitative distribution is altered in progressive diabetes." (PMID 28210227, 2017).
breast carcinoma (2 papers, 2022 to 2023). "The results showed that SLC17A9 was highly expressed in 12 cancer types, including breast cancer, colonic adenocarcinoma, and LIHC." (PMID 35957868, 2022).
hepatocellular carcinoma (2 papers, 2021 to 2022). A malignant tumor that arises from hepatocytes. "The core of our article is to discuss the expression of SLC17A9 in hepatocellular carcinoma and further transfect siRNA to verify it by in vivo experiments." (PMID 35957868, 2022).
lung carcinoma (2 papers, 2013 to 2014). "Recently, by using transfecting human T cells with shRNA for SLC17A9, we have demonstrated the involvement of exocytosis in ATP release caused by activation of T cell receptor, as well as ATP release from lung cancer cells caused by TGF-ß1." (PMID 23577075, 2013). "SLC17A9 is responsible for exocytosis of ATP, in the form of ATP-containing vesicles, and is expressed in PC12 cells, type II taste cells, biliary epithelial cells, T lymphocytes, and lung cancer cells." (PMID 23577075, 2013).
prostate carcinoma (2 papers, 2021 to 2023). A carcinoma that arises from epithelial cells of the prostate gland. "For example, in prostate cancer, LINC01679 suppresses tumor progression by regulating miR-3150a-3p/SLC17A9 axis." (PMID 36941990, 2023).
cervical cancer (1 paper, 2022). A primary or metastatic malignant neoplasm involving the cervix. "Low SLC17A9 expression was found in 21 cancers, including cervical cancer and cholangiocarcinoma." (PMID 35957868, 2022).
colon cancer (1 paper, 2022). "Past studies have implicated SLC17A9 upregulation in gastric, liver, and colon cancer." (PMID 35957868, 2022).
disseminated superficial actinic porokeratosis (1 paper, 2023). Disseminated superficial actinic porokeratosis (DSAP) is the most common form of porokeratosis characterized by the presence of several small annular plaques with a distinctive keratotic rim found most commonly on sun-exposed areas of the skin, particularly the extremities. "Of note, SLC17A9, mapped by a DMR unique to the at-birth analyses of infants of the higher latitude subgroup born in winter, is associated with a skin-specific autoinflammatory disease, disseminated superficial actinic porokeratosis (DSAP)." (PMID 37697338, 2023).
Human Papillomavirus infection (1 paper, 2022). "KEGG pathway analysis showed that SLC17A9 co-expression was mainly associated with PI3K/Akt signaling pathway, neuroactive ligand-receptor interaction, Human Papillomavirus infection (HPV) infection, MAPK signaling, passive transmembrane transporter activity, and channel activity." (PMID 35957868, 2022).
iron deficiency (1 paper, 2022). "Moreover, the TCGA LIHC dataset was grouped into high and low expression groups to determine the expression difference in iron deficiency-related genes at different SLC17A9 expression levels." (PMID 35957868, 2022).
liver cancer (1 paper, 2022). An epithelial or non-epithelial malignant neoplasm that arises from the liver. "The sensitivity and specificity of predicting SLC17A9 expression in liver cancer were 63.6% and 96%, respectively." (PMID 35957868, 2022). "Effectiveness of SLC17A9 knockdown in liver cancer cell line was determined by Western blot and RT-qPCR analysis that showed stable siSLC17A9." (PMID 35957868, 2022). "We speculate that SLC17A9 may interact with these pathways to promote liver cancer progression." (PMID 35957868, 2022).
lysosomal storage disorders (1 paper, 2022). "Since Cathepsin D deficiency is associated with human lysosomal storage disorders, our studies suggest that lysosomal ATP/SLC17A9 could be involved in lysosomal storage disorders." (PMID 35269509, 2022).
non-alcoholic steatohepatitis (1 paper, 2025). "Additionally, SLC17A9 gene knockout mice demonstrate significant improvements in inflammatory cell infiltration and fibrosis in a model of high-fat diet-induced non-alcoholic steatohepatitis (NASH)." (PMID 41197726, 2025).
renal carcinoma (1 paper, 2025). A carcinoma arising from the epithelium of the renal parenchyma or the renal pelvis. "Parallel studies in renal carcinoma established that the SLC17A9-PTHLH-EMT signaling axis critically drives oncogenic proliferation and invasion." (PMID 40894073, 2025).
schizophrenia (1 paper, 2024). A major psychotic disorder characterized by abnormalities in the perception or expression of reality. "Similarly, the resistance marker cg17221813, located in the gene body of the transport protein SLC17A9, has been associated with treatment-resistant schizophrenia." (PMID 38516266, 2024).
tumor (5 papers, 2020 to 2023). "Together, these results confirmed that SLC17A9 was associated with tumor infiltration by immune cells in LIHC, especially B cells, CD4+ T cells, and macrophages." (PMID 35957868, 2022). "IHC results showed that the protein level of SLC17A9 in tumor tissues was significantly higher than that in adjacent normal tissues." (PMID 35957868, 2022). "The expression level of SLC17A9 was assessed using The Cancer Genome Atlas (TCGA) database and immunohistochemistry of tumor tissues and adjacent normal liver tissues." (PMID 35957868, 2022). "Then, the GEPIA database showed that SLC17A9 expression in tumor samples was significantly lower than that in normal samples." (PMID 34900992, 2021). "In addition to known tumor-promoting genes, e.g., c-MYC, YAP1, RAD51B, TRIB3, SLC17A9, JADE1, we found that NAPRT, encoding a key enzyme for NAD+ biosynthesis from nicotinic acid, was also suppressed in HCC cells by the BRD4 inhibitor." (PMID 35399501, 2022). "SLC17A9 expression correlates with tumor immune infiltration, m6A modification, and ferroptosis in LIHC and may have diagnostic and prognostic value in LIHC." (PMID 35957868, 2022). "In addition, SLC17A9 was significantly downregulated in PCa cells and tumor tissues." (PMID 34900992, 2021).
cancer (3 papers, 2022 to 2024). A tumor composed of atypical neoplastic, often pleomorphic cells that invade other tissues. "Mechanistically, ABI2 serving as a co-activator of transcriptional factor HHEX upregulated SLC17A9 to promote HCC cancer stem cell-like properties and tumorigenesis." (PMID 38844969, 2024). "Hypo-methylated gDMs like MX2, OAS2, SPRED2, ADAP1, and SLC17A9 genes showed significant increased expression in cancer stage IV compared to stage I." (PMID 36329447, 2022). "SLC17A9 is involved in the occurrence and development of various cancers, but its biological role in liver hepatocellular carcinoma (LIHC) is unclear." (PMID 35957868, 2022). "We analyzed the expression level of SLC17A9 in TCGA pan-cancer dataset." (PMID 35957868, 2022).
infectious disease (1 paper, 2023). A disorder directly resulting from the presence and activity of a microbial, viral, or parasitic agent in humans. "Conversely, the remaining three genes carrying homozygous missense variants in the twins–SLC17A9, ZNF678 and ACP5 –had no known link to infectious diseases." (PMID 36972292, 2023).
SLC17A9 also shares sentences with these, for which no sentence is quoted: glaucoma (3 papers); steatosis (3); gastric carcinoma (2); osteoporosis (2); peripheral nerve injury (2); type 2 diabetes (2); Anxiety (1); cholangiocarcinoma (1); colonic adenocarcinoma (1); epilepsy (1); glioma (1); Hyperglycemia (1); Immunodeficiency (1); Insulin resistance (1); liver diseases (1); liver inflammation (1); megakaryoblastic leukemia (1); metabolic disease (1); neuroblastoma (1); neurological disease (1); neuropathy (1); overactive bladder (1); periodontitis (1); schwannoma (1); short bowel syndrome (1).